VDAC1 (voltage dependent anion channel 1)
Diseases named in the same sentence as VDAC1 in open-access papers (continued):
Sharing a sentence is not in itself a finding about the gene and the disease.
thyroid cancer (9 papers, 2014 to 2025). "Loss of function of primary cilia in differentiated thyroid cancer cells increases VDAC1 oligomerization and induces mitochondria-dependent apoptosis." (PMID 36418670, 2023). "Taken together, these results indicate that loss of primary cilia from thyroid cancer cells results in VDAC1 overexpression, increased VDAC1 oligomerization, and upregulated apoptosis." (PMID 33602982, 2021). "Defective ciliogenesis caused by deleting the IFT88 and KIF3A genes from thyroid cancer cell lines increased VDAC1 oligomerization following VDAC1 overexpression, thereby facilitating upregulation of mitochondria-dependent apoptosis." (PMID 33602982, 2021). "Thus, we analyzed the oligomeric status of VDAC1 in KIF3A-deficient or IFT88-deficient thyroid cancer cell lines." (PMID 33602982, 2021). "In thyroid cancer cells, the resulting dysfunction of primary cilia leads to marked upregulation of VDAC1 genes and proteins, VDAC1 oligomerization, and apoptotic cell death." (PMID 36418670, 2023). "During immunofluorescence analysis of VDAC1 and primary cilia in thyroid cancer cells, we found that extramitochondrial VDAC1 localized in the primary cilia." (PMID 33602982, 2021). "Genetic defects in ciliogenesis and the resulting dysfunction of primary cilia in thyroid cancers led to marked upregulation of VDAC1 genes and proteins, VDAC1 oligomerization, and apoptotic cell death." (PMID 33602982, 2021). "In conclusion, we show that LOF of primary cilia in differentiated thyroid cancer cells increases VDAC1 oligomerization and induces mitochondria-dependent apoptosis." (PMID 33602982, 2021). "High level of VDAC1 was observed in various cancers, including cervical, lung, pancreatic, ovarian and thyroid cancers." (PMID 33053689, 2020). "We systematically analyzed the expression pattern of VDAC1 and its interacting genes in breast, colon, liver, lung, pancreatic, and thyroid cancers." (PMID 25333947, 2014). "Additionally, cilia gene knockdown leads to the oligomerization of VDAC1, which can result in cytochrome c release, and VDAC1 inhibition can block the increased apoptosis normally seen in cilia-depleted thyroid cancer cells." (PMID 39263863, 2024). "Furthermore, inhibiting ciliogenesis in thyroid cancer cell lines resulted in VDAC1 oligomerization following VDAC1 overexpression, leading ultimately to apoptosis." (PMID 38260150, 2023). "This led us to hypothesize that VDAC1 expression in the basal body is connected to overexpression of VDAC in thyroid cancer cells showing LOF of primary cilia." (PMID 33602982, 2021). "To explore the role of primary cilia in mitochondria-associated apoptosis in thyroid carcinomas, we examined expression of VDAC1, VDAC2, and VDAC3 mRNA in human PTC cells with or without ciliary loss." (PMID 33602982, 2021). "Paired t-tests indicated that VDAC1 was uniformly up-regulated in tumor tissues across all six cancer types, with a fold change of 1.25 in breast, 1.32 in colon, 1.64 in liver, 1.67 in lung, 1.91 in pancreatic, and 1.14 in thyroid cancers." (PMID 25333947, 2014). "Furthermore, VDAC1 localized with the basal bodies of primary cilia in thyroid cancer cells." (PMID 33602982, 2021). "Therefore, regulation of VDAC1 by ciliogenesis inhibitors or regulators might be a therapy for thyroid cancers." (PMID 33602982, 2021). "First, FN1, IDH2, and VDAC1 were more highly expressed in thyroid cancer tissues than in normal tissues; however, FABP4 and TG were less highly expressed in thyroid cancer tissues." (PMID 36418670, 2023). "Here, we demonstrate a sequential process of cell death in thyroid cancer cells with LOF of primary cilia; this process is characterized by VDAC1 oligomerization, cytochrome c release/increase in intracellular Ca2+ levels, and induction of apoptosis." (PMID 33602982, 2021).
thyroid cancer (continued). "In thyroid cancer cell lines, deletion or knockdown of IFT88 and KIF3A impaired ciliogenesis, enhanced VDAC1 oligomerization following VDAC1 overexpression, and disrupted mitochondrial morphology and function, ultimately promoting mitochondria-mediated apoptosis." (PMID 40389989, 2025). "Notably, the depletion of IFT88 and kinesin family member 3A (KIF3A) enhanced voltage dependent anion channel 1 (VDAC1) oligomerization, thereby promoting mitochondrial-dependent apoptotic cell death in differentiated thyroid cancers." (PMID 40017656, 2025). "The function of VDAC1 in the basal body VDAC1 remains unclear, and its role in regulating mitochondrial VDAC in thyroid cancer cells needs to be verified." (PMID 33602982, 2021). "Firstly, we found that VDAC1 is uniformly up-regulated in tumor tissues compared with normal tissues in breast, colon, liver, lung, pancreatic, and thyroid cancers." (PMID 25333947, 2014). "The expression level of VDAC1 was uniformly up-regulated in tumor tissue compared with normal tissue in breast, colon, liver, lung, pancreatic, and thyroid cancers." (PMID 25333947, 2014). "The expression level of VDAC1 is uniformly up-regulated in tumor tissue compared with normal tissue in breast, colon, liver, lung, pancreatic, and thyroid cancers." (PMID 25333947, 2014).
gastric cancer (8 papers, 2018 to 2025). A primary or metastatic malignant neoplasm involving the stomach. "Interestingly, higher VDAC1 levels have also been linked to malignancies of the biliary tract and in gastric cancer." (PMID 39456237, 2024). "In addition, VDAC1 has emerged as a potential diagnostic marker for colorectal cancer and gastric cancer." (PMID 39456237, 2024).
glioma (8 papers, 2017 to 2024). A benign or malignant brain and spinal cord tumor that arises from glial cells (astrocytes, oligodendrocytes, ependymal cells). "TIMM23 and VDAC1 protein expression was equivalent between astrocytes and glioma cells." (PMID 36438483, 2022). "Considering the poor prognosis of GBM patients, findings presented here point to VDAC1-based peptides as a potential new treatment for GBM and glioma." (PMID 28412744, 2017). "This implies that many patients with glioma may not benefit from death ligand-based treatments, unless caspase-8 protein expression can be elevated, such as by VDAC1-based peptides, as demonstrated here." (PMID 28412744, 2017).
heart failure (8 papers, 2020 to 2025). Inability of the heart to pump blood at an adequate rate to meet tissue metabolic requirements. "Analysis of a human cardiac tissue array derived from MI and chronic heart disease patients opened up an opportunity for us to analyze VDAC1 expression levels in the context of one of the most prevalent cardiac pathologies and a leading cause of heart failure and death." (PMID 33328613, 2020). "Prevention of VDAC1 upregulation in ischemia reperfusion (I/R) resulted in a smaller infarct size and was beneficial for the inhibition of heart failure progress, through a blockage of mitochondrial Ca2+ uptake." (PMID 41411330, 2025).
autoimmune disease (7 papers, 2020 to 2025). A disorder resulting from loss of function or tissue destruction of an organ or multiple organs, arising from humoral or cellular immune responses of the individual to their own tissue constituents. "VDAC1 affects various immune cells, such as T cell metabolism and function, dysregulation of VDAC1 has been linked to autoimmune diseases." (PMID 40052442, 2025). "Moreover, dysregulation of VDAC1 has been linked to autoimmune diseases." (PMID 39456237, 2024). "VDAC1 impact on various cellular processes makes it a critical target for therapeutic intervention in metabolic, inflammatory, and autoimmune diseases." (PMID 39456237, 2024). "Mitochondria represent the energy hub of the cell, and their dysfunction plays a critical role in tumorigenesis and a broad range of other pathologies including AD, CVDs, T2D, and a wide variety of autoimmune diseases, which are characterized by over-expression of the VDAC1 protein." (PMID 33114780, 2020). "Thus, inhibiting VDAC1 oligomerization and preventing mtDNA from passing through the OMM may represent a novel strategy for treating not only autoimmune diseases, such as SLE, but also other diseases." (PMID 33114780, 2020).
cardiac hypertrophy (7 papers, 2020 to 2025). "Other researchers have shown that increased levels of VDAC1 expression in a rat model of cardiac hypertrophy were induced by renal artery ligation." (PMID 39598207, 2024). "Additionally, VDAC1 expression was significantly upregulated in a rat model of cardiac hypertrophy induced by renal artery ligation, and treatment with siRNA against VDAC1 partially mitigated apoptotic cell death." (PMID 39456237, 2024). "In addition, prominent upregulation of VDAC1 expressional levels in a rat model of cardiac hypertrophy induced by renal artery ligation and treatment with siRNA against VDAC1 partially inhibited the observed apoptotic cell death." (PMID 33114780, 2020).
cervix squamous cell carcinoma (7 papers, 2012 to 2023). "The results from the different probes in Biewenga Cervix database also verified high expression of VDAC1 in cervix squamous cell carcinoma by comparison with cervix uteri tissues." (PMID 32436862, 2020). "Cisplatin-induced VDAC1 overexpression in a cisplatin-sensitive cervix squamous cell carcinoma cell line (A431) but downregulation VDAC1 in a cisplatin-resistant cell line (A431/Pt)." (PMID 28824871, 2017). "VDAC1 over-expression was observed in a cisplatin-sensitive cervix squamous cell carcinoma cell line (A431) when exposed to cisplatin, while in a cisplatin-resistant cell line (A431/Pt), the treatment resulted in down-regulation of VDAC1." (PMID 23233904, 2012). "Interestingly, cisplatin upregulated VDAC1 expression in a cisplatin-sensitive cervix squamous cell carcinoma cell line (A431), but down-regulated VDAC1 in a cisplatin-resistant cell line (A431/Pt)." (PMID 33114780, 2020). "Compared with the cervix uteri tissues, VDAC1 was overexpressed in cervix squamous cell carcinoma." (PMID 32436862, 2020).
colorectal cancer (7 papers, 2016 to 2026). A primary or metastatic malignant neoplasm that affects the colon or rectum. "Based on these results, we propose that erastin binds to VDAC1 to disrupt normal mitochondrial function, causing mPTP opening, and eventually leading to caspase-9-dependent apoptosis activation in colorectal cancer cells." (PMID 27171435, 2016). "Collectively, these findings demonstrate that SB4 and SB5 are promising candidates for colorectal cancer therapy by targeting VDAC1/PHB/MMP9." (PMID 41179704, 2025). "This study suggests that newly synthesized depside compounds suppress the progression of colorectal cancer by directly targeting VDAC1/PHB/MMP9." (PMID 41179704, 2025). "On the other hand, over-expression of VDAC-1 augmented erastin-induced ROS production, mPTP opening, and colorectal cancer cell apoptosis." (PMID 27171435, 2016). "Caspase inhibitors, the ROS scavenger MnTBAP, and mPTP blockers (sanglifehrin A, cyclosporin A and bongkrekic acid), as well as shRNA-mediated knockdown of VDAC-1, all significantly attenuated erastin-induced cytotoxicity and apoptosis in colorectal cancer cells." (PMID 27171435, 2016).
diabetic cardiomyopathy (7 papers, 2016 to 2025). Diabetic cardiomyopathy is a disorder of the heart muscle in people with diabetes. "Among various mechanisms that are implicated in the development of diabetic cardiomyopathy, it has been demonstrated that H19/miR-675 axis modulates apoptosis of cardiomyocytes by affecting voltage-dependent anion channel 1 (VDAC1)." (PMID 35207562, 2022). "The pathways of neurodegeneration/multiple diseases and diabetic cardiomyopathy were also significant pathways and shared altered proteins such as Atp2a32, Uqcr10, Ndufa12, Vdac1, and Vdac3." (PMID 35565902, 2022). "Furthermore, silencing VDAC1 expression using lncRNA-H19/miR-675 has been reported to regulate high glucose-induced apoptosis by targeting VDAC1, suggesting a novel therapeutic strategy for diabetic cardiomyopathy." (PMID 39456237, 2024).
leukemia (7 papers, 2016 to 2024). A malignant (clonal) hematologic disorder, involving hematopoietic stem cells and characterized by the presence of primitive or atypical myeloid or lymphoid cells in the bone marrow and the blood. "Overall, VDAC1 interactions with pro-survival proteins support anabolic metabolism and inhibit apoptosis thus maintaining leukemia growth." (PMID 36330491, 2022). "Combined treatment of acute promyelocytic leukemia (APL) cell line HL-60 with melatonin and retinoic acid decreases VDAC1 expression, suggesting its leukemia-promoting role." (PMID 36330491, 2022). "Moreover, UCK1, SLC25A38, VDAC1 in our signature have been reported to be involved in proliferation or apoptosis of leukemia cell lines." (PMID 27903973, 2017). "Interestingly, common transcriptional factors involved in leukemia are shared in the regulatory sequences of VDAC1 gene and VDAC1P8 pseudogene, suggesting that both could play a role in this pathology." (PMID 37344914, 2023). "Overall, these results suggest that VDAC1 and the pseudogenes VDAC1P8 and VDAC1P11 share a common transcriptional regulatory pattern in the onset of leukemia." (PMID 37344914, 2023). "This is the first demonstration of VDAC1 and MAVS over-expression in leukemia." (PMID 27078856, 2016). "Since in leukemia the expression of VDAC1P8 is considerably higher than in healthy tissue, this pseudogene could be responsible for, or at least contribute to, the down-regulation of VDAC1 in AML." (PMID 37344914, 2023).
liver fibrosis (7 papers, 2023 to 2026). "It has been reported that the oligomerization of VDAC1 and subsequent mtDNA release are restricted by the ubiquitination of VDAC1 in liver fibrosis." (PMID 40369168, 2025). "Liver fibrosis was inhibited by parkin-mediated ubiquitination of VDAC1 at certain locations, which stopped VDAC1 oligomerization and mtDNA release." (PMID 39114669, 2024). "Here, we investigated the role of Parkin, an important regulator of mitochondria, and its regulation of VDAC1-mediated mtDNA release in liver fibrosis." (PMID 36658227, 2023). "Our results demonstrated that Parkin restricts both mtDNA release into the cytosol and STING activation by ubiquitinating VDAC1 and thus preventing its oligomerization in liver fibrosis." (PMID 36658227, 2023). "Mitochondrial DNA (mtDNA) released through protein oligomers, such as voltage-dependent anion channel 1 (VDAC1), triggers innate immune activation and thus contributes to liver fibrosis." (PMID 36658227, 2023). "The circulating mitochondrial DNA (mtDNA) and protein levels of liver Parkin and VDAC1 were upregulated in patients with liver fibrosis." (PMID 36658227, 2023). "We propose that the ubiquitination of VDAC1 at a specific site by Parkin confers protection against liver fibrosis by interrupting VDAC1 oligomerization and mtDNA release." (PMID 36658227, 2023). "Furthermore, they suggest that Parkin prevents liver fibrosis by ubiquitinating VDAC1 at a particular location, which halts VDAC1 oligomerization and prevents mtDNA release." (PMID 41415310, 2025). "(2023) found that E3 ubiquitin ligase Parkin ubiquitinates voltage-dependent anion channel 1 (VDAC1) at specific sites, preventing liver fibrosis by disrupting its oligomerization and mtDNA release." (PMID 41438738, 2025). "Collectively, our data have unveiled a unique role of Parkin in the regulation of mtDNA release through VDAC1 oligomerization and STING activation in liver fibrosis." (PMID 36658227, 2023).
myocardial ischemia (7 papers, 2009 to 2025). A disorder of cardiac function caused by insufficient blood flow to the muscle tissue of the heart. "Under conditions of cardiac ischemia/reperfusion, upregulated VDAC1 expression can increase myocardial cell damage." (PMID 40799639, 2025). "It has been reported that miR-183-5p protects against myocardial ischemia/reperfusion-induced heart injury by repressing voltage-dependent anion channel 1 (VDAC1)." (PMID 34674708, 2021). "Resveratrol also prevents MPTP opening in myocardial ischemia/reperfusion injury, which was achieved by regulating voltage-dependent anion channel 1 (VDAC1)." (PMID 31426434, 2019). "Activation of VDAC by other MAPKs has been reported; p38 MAPK inhibition significantly reduced the phosphorylation of VDAC1 in a rabbit model of myocardial ischemia and reperfusion." (PMID 19847302, 2009). "Nevertheless, the specific mechanism by which PUE may enhance mitochondrial function following myocardial ischemia–reperfusion through VDAC1 remains unclear." (PMID 39730981, 2024). "However, inactivation of glycogen synthase kinase-3β was shown to reduce coupling of the IP3-receptor to VDAC1 in cardiomyocytes and to reduce mitochondrial Ca2+ uptake during cardiac ischemia-reperfusion." (PMID 34483974, 2021).